INS (insulin)
Diseases named in the same sentence as INS in open-access papers (continued):
Sharing a sentence is not in itself a finding about the gene and the disease.
Obesity (continued). "Here, we show that β cell expression of the peptide hormone cholecystokinin (CCK) is necessary and sufficient for obesity-associated PDAC progression in mice and that CCK expression - rather than insulin - correlates strongly with enhanced tumorigenesis." (PMID 41760660, 2026). "In contrast, deletion of α-Parvin in skeletal muscle caused a striking reduction in muscle glucose uptake during an insulin clamp in lean mice which was not exacerbated by diet-induced obesity." (PMID 41577027, 2026). "While eplerenone produced clear cardiorenal protective effects in our model of obesity, we acknowledge the absence of parallel improvements in systemic blood pressure and whole‐body insulin tolerance." (PMID 41042601, 2026). "Since unresolved ER stress in obesity drives hepatic lipogenesis and inflammatory signaling, the alleviation of ER stress by CU262 would contribute to reduced lipid synthesis and improved insulin sensitivity in the liver." (PMID 41596930, 2026). "ID and hypoadiponectinaemia are not always consequences of obesity and can also occur in lean animals, just as obese animals can have normal total adiponectin concentrations and insulin sensitivity status." (PMID 40257424, 2026). "Obesity is not merely a condition of excess body weight, but a complex, multifactorial disorder characterized by chronic low-grade inflammation, insulin resistance, dyslipidemia, and systemic metabolic dysregulation." (PMID 40867531, 2025). "The BMI-stratified analysis revealed significant differences in ESS, OSA indices (AI, HI, AHI), HbA1c, C-peptide, insulin, IGFBP4, and leptin levels in the obese group, consistent with obesity being an independent contributor to OSA severity and metabolic dysregulation." (PMID 41458545, 2025). "In this study, 4-HIL therapy in mice with diet-induced obesity displayed positive effects on metabolic parameters, which is consistent with the previously reported insulinotropic effects of 4-HIL (improved glucose tolerance and insulin sensitivity)." (PMID 40917356, 2025). "In obesity mouse model, administration of the IL-6 receptor (IL-6R) inhibitor tocilizumab (TCZ) has been shown to significantly mitigate weight gain, regulate adipose tissue hypertrophy, enhance insulin sensitivity, and promote improved glucose tolerance." (PMID 40519917, 2025). "The inflammatory response triggered by obesity can lead to adipose tissue lesions, activation of the renin-angiotensin-aldosterone system (RAAS), sympathetic nervous system (SNS) hyperactivity, insulin resistance, vascular dysfunction and renal pathology, thereby elevating blood pressure." (PMID 40433411, 2025). "Also, metabolic disorders such as obesity and T2DM involve altered levels of adiponectin, which promotes insulin sensitivity and regulates glucose and fatty acid catabolism." (PMID 40662170, 2025). "Since hyperinsulinemia suppresses growth hormone release, the sustained elevation in insulin levels during exercise may have contributed to the overall lower growth hormone and consequently IGF‐1 response we observed in the participants with obesity." (PMID 40574473, 2025). "An ultra-concentrated 10 g (40 kcal) WP formulation as a WPM, provided as an RTD solution and consumed 15 min ahead of a lunch meal in people with T2D and overweight or obesity, reduced PPG, increased PP insulin, GLP-1, and BCAA response, and induced an early delay in GE." (PMID 39852403, 2025). "Mice that lack the BBS chaperonin-complex protein BBS12 also develop obesity but expand the adipose tissue by hyperplasia and retain normal glucose tolerance and insulin sensitivity." (PMID 40836034, 2025).
Obesity (continued). "Moreover, our findings indicate that normal-weight women and those with metabolically healthy obesity exhibited similar key metabolic parameters, including HOMA-IR and insulin levels." (PMID 40422896, 2025). "In obese and/or insulin-resistant individuals, fasting ATBF is lower than in healthy normal-weight individuals and its responsiveness to nutrients is reduced in individuals with obesity." (PMID 41227175, 2025). "In obesity and IR, adipokine profiles are altered, with molecules such as CTRP3 (which enhances insulin sensitivity via AMPK activation) and WISP1 (which impairs insulin signaling through IRS-1 phosphorylation) playing opposing roles." (PMID 40426647, 2025). "In mouse models of both genetic and dietary obesity, stimulation of proteasomal activity by adenovirus-mediated expression of Nrf1 or the proteasome activator PA28a to enhance proteostasis in BAT resulted in obviously improved insulin sensitivity." (PMID 40703332, 2025). "The existence of the “metabolically healthy obesity (MHO)” phenotype further complicates interpretation, as some obese individuals may maintain preserved insulin sensitivity and relatively low systemic inflammation, which our analysis could not disentangle." (PMID 41255642, 2025). "The studies used different drug formulations and treatment durations, and while all focused on obesity as a model, the baseline degree of obesity and insulin resistance was not uniform across all trials." (PMID 40941356, 2025). "Recently, the same team investigated the plasticity of insulin sensitivity, gene expression, and DNA methylation in the skeletal muscle of individuals with obesity with and without T2D undergoing bariatric surgery." (PMID 40862085, 2025). "Conditions of obesity or excessive nutrient intake induce ER stress, production of ROS, and accumulation of ceramides, which activate the NF-κB and JNK pathways, leading to insulin signaling inhibition." (PMID 40893881, 2025). "In a study enrolling patients with obesity and T2D, short-term aerobic exercise improved insulin action, specifying that this effect was due to an increase in peripheral insulin sensitivity rather than from hepatic insulin sensitivity." (PMID 40697264, 2025). "Our results suggest that ablation of adipocyte FAM20C reduces basal lipolysis in obesity, likely due to improved insulin sensitivity, without affecting catecholamine responsiveness." (PMID 41148235, 2025). "Another study showed that diet induced obesity in FGF21 liver‐specific but not FGF21 adipocyte‐specific KOs led to an increased insulin resistance but decreased brown adipose tissue‐mediated glucose metabolism." (PMID 39962359, 2025). "(2017) showed that, compared to normal-weight adolescents with PCOS, a group of adolescents with obesity and PCOS had significantly lower levels of SHBG and HDL-C and significantly higher levels of triglycerides, leptin, fasting insulin, LDL-C and free testosterone." (PMID 40491594, 2025). "When mice were fed a control LFD, female Ctrp10-KO mice developed obesity with age; increased adiposity, however, did not impair insulin action and glucose and lipid metabolism." (PMID 37961647, 2025). "Pathway analysis of differentially phosphorylated proteins identified enrichment in integrin-mediated cell adhesion, insulin signaling, and regulation of the actin cytoskeleton, suggesting a critical role for FAM20C in these processes under pathological conditions of obesity." (PMID 41148235, 2025). "Individuals with mild obesity showed stronger improvements in insulin metabolism, although no clear BMI-stratified differences were observed for glucose outcomes." (PMID 41356824, 2025). "Notably, the elevated complement C3 and α2-MG levels in the obesity and T2DM+obesity groups corresponded with elevated insulin and glucose levels." (PMID 40487757, 2025).
Obesity (continued). "In clinical trials, tirzepatide has demonstrated dose‐dependent efficacy in people with obesity, T2D or both, in terms of glycated haemoglobin (HbA1c) level reduction and bodyweight reduction compared with placebo, GLP‐1 receptor agonists and basal insulin." (PMID 40555920, 2025). "Our goal with using this approach in both HFD-only and HFD + STZ cohorts was to investigate obesity-driven dysfunction from STZ-mediated β-cell injury and to resolve insulin resistance-specific circulating signatures and pathway shifts that have significant translational relevance." (PMID 41002949, 2025). "In the early stages of obesity, there is evidence for increased β-cell hyperplasia to compensate for increased insulin demand in non-diabetic individuals." (PMID 40134803, 2025). "Researchers have determined that a significant decrease in hepatic steatosis, body fat, and plasma triglycerides improves glucose tolerance, insulin sensitivity, and enhanced fat lipolysis in TMPRSS6−/− mice, which provides information regarding the importance of MT2 and iron regulation in obesity." (PMID 40821629, 2025). "Nonetheless, sevelamer did not affect levels of these metabolites, indicating that this drug does not improve insulin sensitivity and lipid levels by reverting concentrations of these metabolites in subjects with obesity to those in lean subjects." (PMID 40666326, 2025). "Studies in nonobese healthy individuals or people with or without obesity or T2D using hyperglycemic clamps showed that endogenous IAPP does not affect insulin sensitivity." (PMID 39998445, 2025). "Compared to those with low intake of chicken protein, individuals with a higher intake demonstrated an adverse lipid profile and a higher prevalence of carotid plaques, with no obvious difference in obesity and insulin sensitivity." (PMID 39949981, 2025). "We provide evidence for a potential link between insulin-controlled GDM and obesity." (PMID 39384641, 2025). "Of note, inflammation of AT alone is sufficient to induce FFA release into the circulation and other pathways leading to AT lipolysis independent of insulin have been shown to be dysregulated in a context of obesity." (PMID 40905018, 2025). "Unlike women with obesity and PCOS, weight loss is not a suitable intervention to increase insulin sensitivity in lean women with PCOS." (PMID 41341431, 2025). "Importantly, chronic CD36 membrane localization, often seen in obesity, enhances FFA influx, promoting intramyocellular lipid accumulation that impairs insulin-stimulated GLUT4 translocation and exacerbates local insulin resistance." (PMID 41002965, 2025). "Insulin and IGF-1, often elevated in obesity, may further enhance central and peripheral HPG activation." (PMID 40933693, 2025). "In obesity, the NOTCH signaling pathway is activated in preadipocytes, which is responsible for weight gain and disruption of glucose homeostasis, and decreases insulin sensitivity in white adipose tissues." (PMID 40863244, 2025). "In metabolic disease states such as obesity and diabetes, circulating nonesterified fatty acids (NEFAs) rise due to insulin resistance or increased adipose lipolysis, driving enhanced FA uptake into cardiomyocytes via transporters such as CD36." (PMID 40898242, 2025). "This suggests that a few generations of HFD can disrupt glucose-insulin homeostasis but is not sufficient to induce offspring obesity." (PMID 41220714, 2025). "Although Treh KO suppressed serum trehalose clearance, it provided no additional anti-obesity benefits or insulin tolerance conferred by i.p. trehalose treatment." (PMID 40529415, 2025). "The global surge in obesity is undeniably contributing to the increasing prevalence of T2DM, a chronic and progressive metabolic disorder characterized by the body’s inability to produce sufficient insulin or to effectively utilize the insulin it produces." (PMID 41150735, 2025).
Obesity (continued). "Previous research suggests that GUDCA administration improves obesity and glucolipid metabolism, while TCA stimulates secretion of glucagon-like peptide-1(GLP-1) and peptide YY (PYY), enhances satiety, and improves insulin sensitivity." (PMID 41306672, 2025). "While CBG has been identified as being regulated by metabolic factors such as obesity and insulin secretion, there is little evidence from humans with CBG null mutations or from mice lacking CBG that deficiency alters cardiometabolic risk." (PMID 39788946, 2025). "A systematic review article on the effects of FMT on obesity and MS including three randomized placebo-controlled studies with 76 patients reported that FMT improved peripheral insulin sensitivity in six weeks for patients receiving FMT compared to the placebo control." (PMID 39901991, 2025). "Multiple clinical studies have investigated PYY’s involvement in glucose metabolism, appetite regulation, and insulin sensitivity among individuals with and without obesity or T2D." (PMID 41228539, 2025). "Furthermore, IH and sleep fragmentation also induce metabolic dysregulation, impairing insulin sensitivity, promoting adipose inflammation, and increasing leptin resistance which contribute to the bidirectional link between OSA and obesity/metabolic syndrome." (PMID 41517455, 2025). "In obesity, AMPK is impaired by excess nutrient availability in the long term, leading to decreased oxidation of fatty acids and increased lipogenesis, which increases fat storage and insulin resistance." (PMID 40218884, 2025). "Multiple labs have shown that the net effect of subcutaneously injecting all postbiotics prepared from an upper gut bacterial extract improved glucose and insulin tolerance in both male and female mice with or without obesity." (PMID 39235984, 2025). "MHO (approximately 30% of obesity) is characterized by obesity without obesity-related metabolic abnormalities, such as hyperglycemia, hypertension, dyslipidemia, and decreased insulin sensitivity." (PMID 40376303, 2025). "Compared with patients initiated on insulin, patients initiated on SGLT2i had a higher prevalence of CV comorbidities and proteinuria, whereas patients initiated on GLP1RA had a higher prevalence of obesity." (PMID 39860655, 2025). "This divergence from canonical obesity-induced inflammation models suggests macrophage Gq signaling primarily targets the insulin secretion axis rather than peripheral insulin resistance." (PMID 41278909, 2025). "A 6-week clinical study (mango flesh, 400 g/day) in participants with obesity resulted in reduced HbA1c (p = 0.006), despite no changes in fasting insulin or glucose." (PMID 39940348, 2025). "It is not obesity but rather cycling estrogen levels and the insulin sensitivity of abdominal adipocytes that protects obese young women from metabolic diseases and breast cancer." (PMID 41514592, 2025). "In individuals who were metabolically healthy and with obesity (gastric banding = 8 or RYGB = 10), the MMT responses of plasma glucose, insulin, and c-peptide (to estimate hepatic insulin extraction; %HIE), incretins (GIP, aGLP-1), and PP were assessed 4–8 weeks prior to and following surgery." (PMID 41155711, 2025). "Studies indicate that obesity may promote the development and progression of TNBC through mechanisms involving immune microenvironment modulation, fatty acid metabolism, and insulin signaling pathways." (PMID 41269404, 2025). "The present study demonstrates that BMI ≥ 22 kg/m was related to higher risk of CMD with higher truncal fat, worsened lipid profile, greater insulin insensitivity when compared with those without obesity." (PMID 40781458, 2025). "Furthermore, Wei Ying’s group demonstrated that in obesity and T2DM, islet macrophages promote β-cell proliferation via PDGF signaling but simultaneously impair insulin secretion." (PMID 40791590, 2025).
Obesity (continued). "Additionally, the increase in zinc-α2-glycoprotein levels in obesity and T2DM+obesity groups were consistent with the IR among these individuals compared to the insulin-sensitive healthy controls." (PMID 40487757, 2025). "Experimental studies have shown that Klotho-deficient mice exhibit widespread tissue atrophy, particularly in the liver and adipose tissue and reduced insulin secretion, despite the absence of obesity." (PMID 41303567, 2025). "The methylation patterns at the promoter regions of these genes that are relevant for adipose tissue biology, appetite regulation, and insulin sensitivity differ between children with and without obesity." (PMID 41032651, 2025). "This interplay is recognized as a key driver of metaflammation, as ATMs actively contribute to systemic low-grade inflammation in obesity through the secretion of pro-inflammatory cytokines such as TNF-α, IL-6, and IL-1β, which are major instigators of the insulin resistance phenomenon." (PMID 41226484, 2025). "Both in overall and time point analyses, maternal lipids, HOMA‐IR, HbA1c and insulin were all significantly higher among women with obesity than in women without obesity." (PMID 40078195, 2025). "By increasing insulin secretion, inhibiting glucagon, and decreasing the consumption of calories through decreased gastrointestinal motility and central anorectic processes, GLP-1 receptor agonists like semaglutide have anti-obesity benefits." (PMID 40649920, 2025). "Knockout mice lacking the SCD1 gene exhibit resistance to diet-induced obesity, accompanied by enhanced metabolic rate and insulin sensitivity." (PMID 40302672, 2025). "Using a non-diabetic mouse model of obesity, Leptinob/ob, Davis and colleagues identified upregulation of islet transcription factor, FoxM1, accompanied by higher circulating insulin levels and lower plasma glucose." (PMID 40134803, 2025). "Studies comparing postprandial insulin secretion in patients with GDM, normal weight, and obesity to those without GDM and healthy pregnancies indicate an increase in insulin levels and resistance in patients with GDM and obesity." (PMID 40724491, 2025). "In adults with OSA and obesity, AHI was inversely correlated with adipose tissue insulin sensitivity, without association with whole‐body insulin sensitivity assessed by the Matsuda index." (PMID 40365648, 2025). "In contrast, males had higher obesity rates and were more likely to lack regular follow-up or rely on injections rather than insulin pumps." (PMID 40869603, 2025). "Children in the MAFLD group had higher levels of fasting insulin (FINS), HOMA-IR, fasting C-peptide, leukocyte (WBC), HbA1c, alanine aminotransferase (ALT), and aspartate aminotransferase (AST) compared to the simple obesity group." (PMID 39980852, 2025). "Specifically, an inverse relationship between CRF and HS with fasting insulin, insulin resistance and beta cell function have been established, the later independent of obesity." (PMID 41276872, 2025). "Furthermore, we provide the first evidence that E2 directly impairs insulin-stimulated glucose uptake in SAT from men, a potential mechanistic link between aromatase activity and metabolic dysregulation in obesity." (PMID 39833659, 2025). "Hypothalamic ventricular administration of EPO in aged obese mice decreased food intake and obesity, improved metabolic function, and reversed impairments in glucose tolerance and insulin sensitivity without increasing hematocrit." (PMID 39996752, 2025). "BMI-stratified analyses revealed that the inverse association between fasting insulin and HGS persisted in both sexes, regardless of obesity status, with a more substantial effect observed in the lower BMI group." (PMID 41464556, 2025). "To determine whether the anti-obesity effects of tryptamine improved glucose metabolism, we performed a glucose tolerance test (GTT) and analyzed insulin signaling in long-term HFD-fed mice." (PMID 39941095, 2025).